PECAM1 (platelet and endothelial cell adhesion molecule 1)
Diseases named in the same sentence as PECAM1 in open-access papers (continued):
Sharing a sentence is not in itself a finding about the gene and the disease.
COVID-19 (29 papers, 2020 to 2025). A disease caused by infection with severe acute respiratory syndrome coronavirus 2. "The LA induced increase in coagulation factor III (CFIII), fibrinogen, plasminogen activation inhibitor-1 (PAI-1), TFPI and soluble PECAM-1/CD31 levels are also noted in severe COVID-19 associated thrombosis as are the thrombocytopenia and an elevated activated clotting time." (PMID 35502320, 2022). "HUVEC supernatants stimulated with serum from patients with severe COVID-19 exhibited elevated levels of sICAM-1, sVCAM-1, P-selectin, sE-selectin, PECAM-1, tissue factor, and thrombomodulin compared to those stimulated with control medium." (PMID 41583455, 2025). "Knowing that GT-73 can covalently bind to PECAM-1 and that it most likely affects its function, we tested GT-73 in a pathology model that leads to severe/terminal stages of COVID-19: ARDS." (PMID 34361736, 2021). "In addition, the authors noted platelet accumulation, an increased expression of platelet endothelial cell adhesion molecule 1 (PECAM-1), and increased tissue factor and von Willebrand factor in the COVID-19 brains." (PMID 37533859, 2023). "Another study by the same authors showed a significant increase in serum protein leakage, platelet accumulation as well as increased expression of platelet endothelial cell adhesion molecule-1 (PECAM-1) and von Willebrand factor in patients that died from COVID-19 compared with control subjects." (PMID 36929707, 2023). "Endothelial cells are abundant in the lung tissue, so PECAM1 may change in the lung tissue of COVID-19 patients and involve in COVID-19 pathological change." (PMID 36199786, 2022). "There was also a moderate correlation between the plasma soluble PECAM-1 values and plasma levels of AAT in COVID-19 patients." (PMID 36084115, 2022). "The surface expression of PECAM-1, an inhibitory adhesion receptor that is cleaved from the leukocyte surface in inflammatory conditions, was not significantly changed in patients with COVID-19." (PMID 38193050, 2023). "Higher circulating DAMPs (e.g., ds-DNA, HMGB1), and endothelial proteins such as E-selectin, PECAM-1, or ICAM-1 provide a mechanistic link for the prothrombotic state and hepatic portal thrombosis, pulmonary thrombosis induced by LA, which is similar to COVID-19 autopsies." (PMID 35502320, 2022). "Moreover, cell adhesion markers such as ICAM1, PECAM1, and SELE were markedly, and significantly, upregulated in COVID-19, influenza, and non-influenza viral myocarditis (FDR < 0.001)." (PMID 36371548, 2023).
Sepsis (28 papers, 2013 to 2025). Sepsis is defined as life-threatening organ dysfunction caused by a dysregulated host response to infection. "Sepsis-associated disseminated intravascular coagulation (DIC) could inhibit macrophage pyroptosis through platelet endothelial cell adhesion molecule-1 (PECAM-1), thus restoring vascular barrier integrity." (PMID 35572571, 2022). "PECAM1 connects adjacent endothelial cells and regulates inflammation, leukocyte migration, and vascular responses during sepsis." (PMID 40563443, 2025). "EC permeability was related to other genes, such as, Cldn5 (claudin 5) and Pecam-1/CD31 (platelet EC adhesion molecule), also significantly upregulated in septic capEC, suggesting that sepsis induces gene expression related to capillary permeability." (PMID 34638535, 2021). "Also, the application of a protective MV strategy in animals with sepsis-induced lung injury prevented the increase of circulating serum levels of sPECAM1, which was associated with a lower histological lung injury score and a higher PECAM1 protein content in the lungs." (PMID 24588994, 2014). "Levels of circulating PECAM1 particles shed from damaged endothelial cells have been reported as a marker of endothelial injury and to be present in various inflammatory diseases, including sepsis." (PMID 24588994, 2014). "Since PECAM1 is required for restoring endothelial continuity, targeting PECAM1 integrity may open new therapeutic approaches for sepsis and ARDS." (PMID 24588994, 2014). "MV and sepsis decreased PECAM1 protein content in the lungs depending on the ventilatory strategy." (PMID 24588994, 2014). "Since its cloning in 1990, there has been enormous progress in understanding the biology of PECAM1 and there is now clear evidence for its involvement in regulating leukocyte migration and inflammatory and vascular responses in numerous disease processes, including sepsis." (PMID 24588994, 2014). "Therapeutic strategies aimed at modulating glial activation states (e.g., restoring M2 or A2 phenotypes), blocking inflammatory signaling (e.g., TGF-β, PECAM1), or reinforcing BBB structural integrity may hold promise for mitigating CNS complications in sepsis." (PMID 41030458, 2025).
pancreatic cancer (27 papers, 2013 to 2025). "To confirm the increased population as TAMs, we sorted the CD11b + F4/80 + cells from the pancreatic tumors using a FACS sorter and quantified the expression of some TAM markers, such as HIF-1α, CCL2, and PECAM1, with qRT-PCR." (PMID 34150748, 2021).
Obesity (22 papers, 2012 to 2026). Accumulation of substantial excess body fat. "Genes associated with leukocyte migration, such as Alcam, Icam1, Pecam1 and Vcam1, were induced in brain art ECs by sustained obesity." (PMID 36400935, 2022). "Relative to other brain ECs, art ECs showed enriched expression of several leukocyte adhesion genes, and Vcam1, Pecam1, Alcam and Icam1 were upregulated in art ECs in obesity." (PMID 36400935, 2022). "In our study, obesity-induced damage to the heart was associated with NF-κB activation and increased in ICAM-1, PECAM-1, TNF-α, IL-1β, and IL-6 expression levels." (PMID 35625374, 2022). "Overall, inflammation may play the role of a bridge between obesity and Alzheimer’s disease, and the four hub genes above (MMP9, PECAM1, C3AR1, and IL1R1) are critical to this." (PMID 36568118, 2022). "Platelet endothelial cell adhesion molecule-1 (PECAM-1/CD31) plays a role as an adhesion and signaling molecule with several roles in vascular and inflammatory processes, and its levels are increased in young men with severe obesity." (PMID 34884217, 2021).
coronary artery disease (20 papers, 2012 to 2024). "PECAM1 was shown to be associated with LYM in coronary artery disease, chronic venous disease during pregnancy and tumors." (PMID 38638428, 2024). "The sEGFR, PECAM-1, sVEGFR-1, and sTIE-2 are implicated in the regulation of fibrotic processes, vascular integrity, and vessel wall homeostasis, considering that most of our patients have been diagnosed with coronary artery disease." (PMID 38674917, 2024). "These genes included Cdh13 and Lpl from Cluster 1; Nfia, Col4a1 and Serpinh1 from Cluster 2; Arhgef12, Col4a2, Scarb1 and Cst3 from Cluster 3; Pecam1 and Aldh2 from Cluster 4, providing plausible molecular basis for the inextricable causal link between age and coronary artery disease." (PMID 35615560, 2022). "Six genes (ABCB1, PLAT, ACE, GH1, PECAM1, and RGS9) known to predispose people to coronary artery disease occur in the cn-LOH regions identified." (PMID 28120895, 2017). "PECAM-1 is a kind of cell adhesion molecule, which plays an important role in coronary artery disease." (PMID 28512385, 2017). "Previous studies suggested a dual function of PECAM1 in the process of coronary arteriosclerosis." (PMID 35054067, 2022).
Hyperglycemia (19 papers, 2012 to 2025). An increased concentration of glucose in the blood. "In vitro studies have confirmed that hyperglycemia causes PECAM-1 loss in retinal endothelial cells." (PMID 34445504, 2021). "PECAM-1 has been described to be degraded by matrix metalloproteinase-2 (MMP-2), an enzyme found to be upregulated by hyperglycemia." (PMID 32964051, 2020). "In this study, it demonstrated that PF could alleviate vascular injuries induced by hyperglycemia fluctuations in terms of the release of TNF-α, PECAM-1, oxidative stress, and the expression of PKCβ1 in HUVECs subjected to intermittent glucose levels and in DM rats with fluctuating hyperglycemia." (PMID 31093316, 2019).
Cerebral ischemia (17 papers, 2015 to 2025). Restriction of arterial blood supply to the brain associated with insufficient oxygenation to support the metabolic requirements of the tissue. "Microvessel hypoperfusion following ischemic stress resulted in a decreased shear stress of brain microvascular endothelial cells (BMECs) and contributed to abnormal expression of PECAM-1 after global cerebral ischemia/reperfusion (I/R) injury." (PMID 33553171, 2020).
Hypertension (17 papers, 2010 to 2026). The presence of chronic increased pressure in the systemic arterial system. "Our data show that long-term mild hypertension is associated with abnormal accumulation of vascular collagen IV, altered PECAM-1 and disruption of astrocyte end-feet associated with vessels." (PMID 31708792, 2019).
lung adenocarcinoma (17 papers, 2014 to 2025). A carcinoma that arises from the lung and is characterized by the presence of malignant glandular epithelial cells. "Three genes (PIK3R1, SPP1, and PECAM1) have a clear correlation with OS in lung adenocarcinoma patients." (PMID 36688087, 2023). "SPP1 is highly expressed in lung adenocarcinoma compared with normal lung tissue, and the high expression of SPP1 is associated with poor prognosis, while the high expression of PECAM1 and PIK3R1 is associated with good prognosis." (PMID 36688087, 2023). "In this study, based on the survival and the hub gene analysis, we found that PECAM-1 expression was low in lung adenocarcinoma tissues, and importantly, PECAM-1 expression was associated with worse prognosis in lung adenocarcinoma." (PMID 36688087, 2023). "Surprisingly, the survival analysis revealed that three genes (PIK3R1, SPP1, and PECAM1) have a clear correlation with OS in lung adenocarcinoma patients." (PMID 36688087, 2023). "It has been found that lung adenocarcinoma exhibits high expression of SPP1 and that this has been associated with poor prognosis, while low expression of PECAM1 and PIK3R1 is associated with poor prognosis (P < 0.05)." (PMID 36688087, 2023). "We found three genes (PIK3R1, SPP1, and PECAM1) that have a clear correlation with OS in the lung adenocarcinoma patient." (PMID 36688087, 2023). "Among the top 10 genes with a high average ΔPCC in lung adenocarcinoma (LUAD), several genes such as CLDN18, ADAMTS8, PECAM1 and SFTPA1 have been known to be associated with LUAD in previous studies." (PMID 32854705, 2020). "In the present study, the effects of the systemic delivery of siRNACD31 on the growth of lung adenocarcinoma xenografts were investigated with the application of 2′-O-methyl-modified siRNACD31-cationic liposome complexes to silence PECAM-1." (PMID 24959215, 2014). "The results of the immunohistochemical examination indicated that PECAM-1 expression was observed in the vasculature of the lung adenocarcinoma xenograft and the lung, liver, heart, brain and kidney tissues." (PMID 24959215, 2014). "Although our current study focuses primarily on lung adenocarcinoma (LUAD) and identifies PECAM1 as a potential prognostic biomarker, these findings collectively underscore the growing importance of subtype-specific biomarkers in NSCLC." (PMID 40361912, 2025). "Demographic, clinical, and pathological characteristics of patients with lung adenocarcinoma in the PECAM-1 high-expression group (PECAM-1+) and the PECAM-1 low-expression group (PECAM-1-)." (PMID 33828969, 2021). "Although the expression of the PECAM-1 protein in the lung, liver, heart, brain and kidney tissues was not decreased, a decrease in PECAM-1 expression was obtained in the lung adenocarcinoma xenografts." (PMID 24959215, 2014).
pulmonary fibrosis (15 papers, 2013 to 2025). Chronic progressive interstitial lung disorder characterized by the replacement of the lung tissue by connective tissue, leading to progressive dyspnea, respiratory failure, or right heart failure. "Among those genes, we found that CAV1 and PECAM1 were specifically expressed in lung tissues, BMP4 and VEGFA were related to angiogenesis, FYN and SPP1 were related to immunity or inflammation, and COL1A1 was closely associated with pulmonary fibrosis according to the GeneCards database." (PMID 37794454, 2023). "By searching the 18 candidate hub genes in GeneCards database, we found that CAV1 and PECAM1 were specifically expressed in lung tissues, BMP4 and VEGFA were related to angiogenesis, FYN and SPP1 were related to immunity or inflammation, and COL1A1 was closely associated with pulmonary fibrosis." (PMID 37794454, 2023).
non-small cell lung carcinoma (14 papers, 2002 to 2026). A group of at least three distinct histological types of lung cancer, including non-small cell squamous cell carcinoma, adenocarcinoma, and large cell carcinoma. "Moreover, a previous study of non-small cell lung cancer patients revealed that high (rather than low) expression of PECAM-1 was associated with improved survival." (PMID 40713559, 2025).
periodontitis (14 papers, 2012 to 2025). An acute or chronic inflammatory process that affects the tissues that surround and support the teeth. "The intersection of these three machine learning approaches revealed six potential biomarkers associated with PANoptosis in periodontitis: PECAM1, CXCR4, SELP, IL2RG, CD48, and ZBP1." (PMID 40612110, 2025). "Previous studies have shown that P. gingivalis can reduce endothelial PECAM-1 expression to disrupt the endothelial barrier in periodontitis." (PMID 37199607, 2023). "The current study found that PECAM-1 was significantly upregulated in periodontitis tissues compared to normal tissues, and possessed up to 25 paired genes in 74 OS-DEGs." (PMID 36148415, 2022). "We also identified three “master” immunosuppression genes, PECAM1, FCGR3A, and FOS, as candidate genes central to immune suppressive pathogenic mechanisms in periodontitis." (PMID 33777111, 2021). "Immunofluorescence assays for the MHC class II marker HLA-DR and the endothelial cell marker PECAM1 (CD31) further confirmed the existence of antigen-presenting endothelial cells in gingival tissues of periodontitis." (PMID 34566966, 2021). "The present data indicate that PECAM1 may play a central role in the pathogenesis of periodontitis partially through exerting effects on both leukocytes and endothelial cells." (PMID 36148415, 2022). "Furthermore, PECAM1 has been identified a potential biomarker for periodontitis diagnosis and prognosis." (PMID 36148415, 2022). "Six of them were identified as key OS-genes (CXCR4, SELL, FCGR3B, FCGR2B, PECAM1, and ITGAL) in periodontitis." (PMID 36148415, 2022). "In the present study, by performing multiple bioinformatics analysis methods, we firstly identified six key OS-genes (CXCR4, SELL, FCGR3B, FCGR2B, PECAM1, and ITGAL) in periodontitis, whose expression levels were significantly upregulated." (PMID 36148415, 2022). "Three “master” immunosuppression genes, PECAM1, FCGR3A, and FOS were identified as candidates pivotal to immunosuppressive mechanisms in periodontitis." (PMID 33777111, 2021). "PECAM1, FCGR3A, and FOS emerged as high-value biomarkers and candidate therapeutic targets for periodontitis." (PMID 33777111, 2021). "The central finding of our study is the identification of three distinct immunosuppression genes, PECAM1, FCGR3A, and FOS, which could be potentially high-value biomarkers or candidate therapeutic targets for periodontitis." (PMID 33777111, 2021). "As shown in the Venn diagram, three significant DEGs, Platelet Endothelial Cell Adhesion Molecule (PECAM) 1, Fc Gamma Receptor (FCGR) 3A, and FOS were found intersecting and considered as potentially most robust immunosuppression genes related to periodontitis." (PMID 33777111, 2021). "PECAM-1 and PTPRC have not been reported in relation to periodontitis or peri-implantitis." (PMID 35581339, 2022).
type 2 diabetes (14 papers, 2010 to 2025). "More recently, treatment of type 2 diabetes with rosiglitazone has been reported to cause decreases in μ-calpain activity, the restoration of platelet PECAM-1 levels and diminished platelet responsiveness to thrombin." (PMID 20040043, 2010).
endometriosis (13 papers, 2012 to 2026). The growth of functional endometrial tissue in anatomic sites outside the uterine body. "Patients with endometriosis and endometrial cancer generally have an increased expression of PECAM-1." (PMID 38274228, 2023). "All primary cultures derived from either control eutopic endometrium and endometriosis lesions were positive for endometrial stroma cell markers CD10 and vimentin and negative for endothelial (PECAM1) and epithelial (EPCAM) markers, indicating they represent the endometrial stromal cell compartment." (PMID 38203610, 2023).
infarction (13 papers, 2015 to 2025). A localised pathological necrosis of tissue resulting from obstruction of the blood supply usually by a thrombus, an embolus, or vascular torsion. "A laser speckle flow imaging system was used to measure cerebral blood flow (CBF) around the ischemic cortex of the infarction, followed by platelet endothelial cell adhesion molecule-1 (PECAM-1/CD31) and isolectin-B4 (IB4) immunofluorescence." (PMID 35369317, 2022).
metastatic tumors (13 papers, 2013 to 2026). "It was previously reported that PECAM-1 is also associated with advanced metastatic tumor progression." (PMID 36688087, 2023).
heart failure (12 papers, 2012 to 2024). Inability of the heart to pump blood at an adequate rate to meet tissue metabolic requirements. "Double staining of ACTA2 and PECAM1 (CD31) identified pericyte abnormalities in patients with heart failure." (PMID 37845397, 2023). "In heart failure research, soluble PECAM-1 was found to be elevated in the majority of patients with severe CHF." (PMID 31936828, 2020).
leukemia (12 papers, 2013 to 2025). A malignant (clonal) hematologic disorder, involving hematopoietic stem cells and characterized by the presence of primitive or atypical myeloid or lymphoid cells in the bone marrow and the blood. "In the present study, we demonstrate that PECAM-1 is tyrosine phospho rylated in its ITIM motifs in various BCR/ABL-expressing cells including primary leukemia cells." (PMID 23233201, 2013). "PECAM-1 is also expressed on various types of leukemias, including acute myeloid leukemia (AML), acute lymphoblastic leukemia (ALL), and chronic lymphocytic leukemia (CLL), and has been implicated in prognosis of CLL, although it remains controversial." (PMID 23233201, 2013). "Thus, its examination in various leukemic cells may shed more light on the significance of PECAM-1 in pathogenesis and prognosis of leukemias." (PMID 23233201, 2013). "The expression of VCAM1, VEGFA, PECAM1, and ICAM1, which promote leukemia cells to cross the BBB, was studied by RT-PCR." (PMID 35256780, 2022). "A subpopulation of the Ph+ B-ALL cell line SUP-B15 presents leukemia stem cells (LSCs) and expresses stem cell markers (CD34, CD38, and c-Kit) and endothelial antigens (Flk-1 and PECAM-1); moreover, LSCs express VE-cadherin after a long-term co-culture on stromal cells." (PMID 33425742, 2020). "Overexpression of PECAM-1 in BCR/ABL-expressing cells, including K562 human leukemia cells, enhanced cell adhesion and partially inhibited imatinib-induced apoptosis involving mitochondria depolarization and caspase-3 cleavage, at least partly, in an ITIM-independent manner." (PMID 23233201, 2013).
fibrosis (11 papers, 2014 to 2025). the formation of excess fibrous connective tissue in an organ or tissue in a reparative or reactive process. "Angiogenesis in vivo was investigated in a murine fibrosis model by staining endothelial vessels for PECAM-1 (CD31)." (PMID 24734240, 2014).